TUBA1A (tubulin alpha 1a)
Diseases named in the same sentence as TUBA1A in open-access papers (continued):
Sharing a sentence is not in itself a finding about the gene and the disease.
diabetes (3 papers, 2018 to 2025). "Four proteins were markedly under-expressed (Hsp60, HspA8, TUBA1A, and ENO1) and linked to the pathogenesis of diabetes or post-translationally modified by O-GlcNAc." (PMID 29867058, 2018). "Nqo2 is an antioxidant that may protect against diabetes-induced endothelial dysfunction, whereas Tuba1a is the gene responsible for producing cytoskeleton protein tubulin, a known target for glyoxalase system defect." (PMID 39896461, 2025). "Novel targets include MYO18A, SEC16A, CCNB1, MAD2L1, hsa-mir-4315, hsa-mir-6134, hsa-mir-9500, KIFC3, FBL (fibrillarin), TUBA1A and GFI1B might have crucial biologic functions in the pathogenesis of patients with diabetes mellitus and obesity." (PMID 36837510, 2023).
glioma (3 papers, 2010 to 2025). A benign or malignant brain and spinal cord tumor that arises from glial cells (astrocytes, oligodendrocytes, ependymal cells). "Like TUBA1A, targeting H19 also appears to suppress glioma cell proliferation and enhance sensitivity to chemotherapy, thereby improving clinical outcomes." (PMID 40974979, 2025). "The top 20 co-expressed neighbors were selected, and the core genes PFN1, CALR, thymosin beta 10 (TMSB10), HLA.A, CD74 (HLADG), HLA.DRA, HLA.B, TUBB, and TUBA1A were found to play pivotal roles in the network, suggesting that immune genes are involved in glioma formation." (PMID 34660294, 2021). "That is the case of genes such as GNB2L1, an anchor protein involved in adhesion and migration of human glioma cells, DPYSL2, a promoter of microtubule assembly and neuronal development, TUBA1A or CFL, which controls cell migration and cell cycle progression." (PMID 20735813, 2010).
Intellectual disability (3 papers, 2020 to 2024). "After consolidating intellectual disability gene lists from two databases and one recent review article, we identified eight LRRK2 interacting proteins that have previously been linked to intellectual disability: ACTB, ACTG1, ATRX, DYNC1H1, HERC2, PPP2R1A, TUBA1A, and YWHAE." (PMID 31963867, 2020).
Cerebellar hypoplasia (2 papers, 2022). Cerebellar hypoplasia is a descriptive term implying a cerebellum with a reduced volume, but a normal shape and is stable over time. "Recently, a large exome sequencing study of children and adults with DWM and cerebellar hypoplasia expanded the list of genes associated with DWM to include TUBA1A, BRAF, SETD2, FOXP1, PUS3, ARMC9, and PIBF1." (PMID 35202430, 2022).
cognitive deficit (2 papers, 2021 to 2024). "In the present study, we found that downregulation of TUBA1A in CIH rats and patients with OSA may be an underlying mechanism for OSA complications, such as cognitive disorders and male hypogonadism." (PMID 34185819, 2021).
coloboma (2 papers, 2024). An abnormality in which a part of a structure in one or both eyes is missing. "TUBA1A may also be a potential therapeutic target for ocular coloboma patients with SALL2 mutations." (PMID 39349437, 2024). "Patients with pathogenic TUBA1A variants and various eye anomalies such as coloboma (PMID: 26130693, PMID: 38502138), microphthalmia and cataracts (PMID: 26294046) have been reported, demonstrating the importance of this gene in eye development, structure and function." (PMID 39495751, 2024).
colon cancer (2 papers, 2023 to 2025). "Therefore, TUBA1A may act as a potential target when TSA is used to treat colon cancer." (PMID 37072452, 2023).
colorectal cancer (2 papers, 2019 to 2023). A primary or metastatic malignant neoplasm that affects the colon or rectum. "MCOLN1 and TUBA1A were associated with both TSA- and colorectal cancer cell line-specific effects." (PMID 37072452, 2023).
glioblastoma (2 papers, 2024 to 2025). The most malignant astrocytic tumor (WHO grade IV). "The knockdown of TUBA1A appears to inhibit glioblastoma cell proliferation and invasion both in vitro and in vivo." (PMID 40974979, 2025). "The critical function of SALL2 in neural differentiation and one of its targets Tuba1a verified in this study may offer potential therapeutic strategy for the diagnosis and treatment of glioblastoma in future." (PMID 39349437, 2024).
infantile spasms (2 papers, 2019 to 2022). A rare epilepsy syndrome characterized by onset of epileptic spasms in infants between 2 and 12 months of age, and rarely up to 24 months. "Concerning epileptic clinical manifestation, West syndrome is the most frequent clinical phenotype at onset in patients carrying TUBA1A and TUBB2B gene mutations." (PMID 31269740, 2019).
Lissencephaly 3 (2 papers, 2022 to 2025). "The ARID1B gene, associated with Coffin-Siris syndrome 1 (MIM: # 135900), and the TUBA1A gene, causative of Lissencephaly 3 (MIM: # 611603), were recurrently mutated." (PMID 41153384, 2025). "Heterozygous missense variants in the TUBA1A gene have been reported in patients with lissencephaly 3 (OMIM # 611603); a cortical malformation caused by neuronal migration defects and characterized by smooth brain surface." (PMID 36672823, 2022).
myopia (2 papers, 2024). "According to our research, patients with pathologic myopia had downregulated expression of XYLT1, VCAN, and SPOCK2 and upregulated expression of TUBA1A and EEF1A1." (PMID 39160465, 2024). "Although there have been no reports that TUBA1A plays a role in the development of myopia, we found a significant increase in TUBA1A expression in the VH of PM patients." (PMID 39160465, 2024). "It is also worth noting that our study describes cases of HM in individuals with variants in genes that have not yet been clearly associated with the development of myopia (TRPV4, TUBA1A, SBDS, KIDINS220)." (PMID 39495751, 2024). "In one (1/18) child, we found genetic variants defined as VUS, and in four (4/18) children, we found (likely) pathogenic variants in the genes TRPV4, TUBA1A, SBDS, KIDINS220, which have not been previously associated with the development of myopia." (PMID 39495751, 2024).
neuroblastoma (2 papers, 2021 to 2023). Neuroblastoma (NB) is the most common solid, extracranial childhood tumor. "Conversely, a transcriptomic study on neuroblastoma SK-N-SH cells revealed that SARS-CoV-2 infection induced a downregulation of several members of building blocks of the cytoskeleton, as well as some of their regulators (i.e., TUBA1A, TUBA4A, TUBB4A, STMN4, TMSB15A, SYNPO2)." (PMID 37896797, 2023).
Obesity (2 papers, 2011 to 2023). Accumulation of substantial excess body fat. "A number of novel obesity candidate genes were also identified (Thbs1, Ppp1r3d, Tmepai, Trp53inp2, Ttc7b, Tuba1a, Fgf13, Fmr) that have inferred roles in fat cell function." (PMID 21915269, 2011).
ovarian carcinoma (2 papers, 2023 to 2024). A malignant neoplasm originating from the surface ovarian epithelium. "Bioinformatics prediction unveiled a close association of GPR137, NDEL1, DYNC1H1, and TUBA1A with ovarian cancer development and prognosis." (PMID 38021163, 2023). "Moreover, by examining clinical data, we found that the expression of four genes, GPR137, NDEL1, DYNC1H1, and TUBA1A, differed significantly between tumor tissues and normal tissues, and their expression levels were significantly associated with poor prognosis of ovarian cancer patients." (PMID 38021163, 2023). "Thus, the findings of the analysis indicate a significant correlation of the expression levels of GPR137, NDEL1, DYNC1H1, and TUBA1A with the advancement and prognosis of ovarian cancer." (PMID 38021163, 2023). "Further, multiple gene correlation analyses revealed a significant positive linear relationship between GPR137 expression in ovarian cancer tissues and the expression levels of NDEL1, DYNC1H1, and TUBA1A." (PMID 38021163, 2023). "The findings of the study indicate that ovarian cancer patients with elevated expression of GPR137, NDEL1, and TUBA1A genes experienced a statistically significant increase in survival time, as demonstrated by Kaplan-Meier survival analysis." (PMID 38021163, 2023).
Rett syndrome (2 papers, 2016 to 2022). A severe neurodevelopmental disorder affecting the central nervous system.
schizophrenia (2 papers, 2012 to 2024). A major psychotic disorder characterized by abnormalities in the perception or expression of reality. "ACTB, CKB, NEFL, INA and GFAP had link to both schizophrenia and depression, while CTSD, HSPA8, NEFM and TUBA1A had link to schizophrenia." (PMID 23272063, 2012). "Expression of the ‘Macroautophagy’ genes AMBRA1, PRKAB1, TUBA1A, TUBB2A, and TUBA4A was restored in the AT-schizophrenia group." (PMID 38648100, 2024).
type 1 lissencephaly (2 papers, 2007 to 2014). "Following the identification of this mutant gene in the mouse, mutations were identified in TUBA1A in type 1 lissencephaly in human." (PMID 24624057, 2014).
Adult onset (1 paper, 2023). Onset of disease manifestations in adulthood, defined here as at the age of 16 years or later. "Recently, the loss of function p.N102D substitution, in heterozygous state in Tuba1a has been reported to reduce Tuba1a and developmental total α-tubulin stability, causing adult onset movement disorder and ataxia in Tuba1aND/+mice." (PMID 37435044, 2023).
Ataxia (1 paper, 2023). Ataxia refers to impaired coordination of voluntary muscle movement. "In this study, we causally link the previously unreported missense mutation p.I384N in TUBA1A, one of the neuron-specific α-tubulin isotype I, to a neurodegenerative disorder characterized by progressive spastic paraplegia and ataxia." (PMID 37435044, 2023). "In the present study, we report on the novel loss-of-function mutation p.I384N in TUBA1A, resulting in progressive spastic paraplegia and ataxia." (PMID 37435044, 2023). "Here we report on the identification of a novel variant in TUBA1A, identified by WES in a subject with ataxia and progressive spastic paraplegia." (PMID 37435044, 2023). "Recently, the heterozygous p.N102D substitution in Tuba1a gene identified by ENU-induced mutagenesis forward genetic screening in mice with locomotor defects, has been reported to cause adult-onset movement disorder and ataxia." (PMID 37435044, 2023).
breast tumor (1 paper, 2024). "However, CYR61, FLRT2, SLIT2, VNN1, MAP1B, MYLK, and TUBA1A gene expressions were high in normal adjacent tissue in comparison with those in breast tumor tissue." (PMID 39596804, 2024).
colorectal adenocarcinoma (1 paper, 2023). The most common type of colorectal carcinoma. "Furthermore, we identified two genes, TUBA1A and MCOLN1, which are associated with TSA and colorectal adenocarcinoma." (PMID 37072452, 2023).
congenital fibrosis of the extraocular muscles (1 paper, 2023). "Congenital fibrosis of the extraocular muscles (CFEOM) affects cranial nerves 3 and 4 and is caused by autosomal dominant missense variants in KIF21A, TUBB3, TUBB2B or TUBA1A or autosomal recessive variants in PHOX2A." (PMID 38500555, 2023).
dementia (1 paper, 2021). Loss of intellectual abilities interfering with an individual's social and occupational functions. "Expression of tubulin alpha 1a (TBA1A) was observed to be significantly higher in rpAD than in other rapid dementia samples, i.e. DFTL, SVD, and r-DLB." (PMID 33618749, 2021).
heart failure (1 paper, 2016). Inability of the heart to pump blood at an adequate rate to meet tissue metabolic requirements. "Supporting the notion that the tubulin network is distorted in heart failure cells, mRNA expression analysis by qPCR confirmed an overall increase in the expression of α1A-tubulin (TUBA1A), β2B-tubulin (TUBB2B), β3-tubulin (TUBB3), γ-1tubulin (TUBG1), and microtubule-associated proteins (MAP4)." (PMID 26725114, 2016).
lower respiratory tract infections (1 paper, 2022). "Indeed, genetic defects in DNAH5, HYDIN, and TUBA1A and others result in primary cilia dyskinesia (PCD); a variety of clinical manifestations including ineffective mucociliary clearance and recurrent lower respiratory tract infections." (PMID 35169120, 2022).
lung carcinoma (1 paper, 2020). "Through our analysis, we also found other eight proteins (ACAT2, PSIP1, TCERG1, DPYSL5, TUBA1A, AKR1B1, ANP32E, and TXNDC17) that have been associated with other cancers, but not in lung cancer." (PMID 32351780, 2020).
non-small cell lung carcinoma (1 paper, 2016). A group of at least three distinct histological types of lung cancer, including non-small cell squamous cell carcinoma, adenocarcinoma, and large cell carcinoma. "The tubulin alpha-1A (TUBA1A) has only been linked to non-small cell lung carcinomas." (PMID 28018022, 2016).
Nystagmus (1 paper, 2021). Rhythmic, involuntary oscillations of one or both eyes related to abnormality in fixation, conjugate gaze, or vestibular mechanisms. "We also thought that TUBB3 and TUBA1A genes should be included in the targeted panel of infantile nystagmus." (PMID 33921132, 2021).
optic nerve hypoplasia (1 paper, 2021). "Similarly, optic nerve hypoplasia has been reported with TUBA1A mutations, thus suggesting that tubulin gene mutations in general can cause optic nerve hypoplasia." (PMID 33806565, 2021).
Pleural effusion (1 paper, 2025). The presence of an excessive amount of fluid in the pleural cavity. "We also identified pleural effusion predictive gene signatures, including TMPRSS3, MS4A7, NAPSA, and IGFBP2, while liver metastasis predictive markers included WFDC2, HSPB1, COX6C, APOE, and TUBA1A." (PMID 39955556, 2025).
Stroke (1 paper, 2019). Sudden impairment of blood flow to a part of the brain due to occlusion or rupture of an artery to the brain. "Our proteomics results show that many cytoskeletal proteins were present at higher-than-normal concentrations in CSF following stroke, including myosins (MYH1/4/8/9 and MYL1), and tubulins (TUBA1A/B/C, TUBA3A, and TUBB4A/B)." (PMID 30645580, 2019).
tumor (16 papers, 2010 to 2025). "The tubulin proteins TUBA1A and TUBB and their heterogeneity has been associated with GBM, whereas DBI maintains high proliferation rates, promoting tumor growth." (PMID 35327982, 2022). "The results showed that the relative expression of CXCL12, CEBPA, and TUBA1A in tumor cells was significantly lower than that in normal cells (all P < 0.05)." (PMID 34225733, 2021). "qRT-PCR examined their relative expression in adjacent normal tissues and tumor tissues, detecting TUBA1A was significantly downregulated in tumor tissues." (PMID 32398968, 2020). "We analyzed TUBA1A expression in CC cells, finding the expression in CC cells is in concert with that in CC tumor tissues." (PMID 32398968, 2020). "NEK2 was altered in 22.9% of analyzed tumor samples and found interacted with the α-tubulin isoforms TUBA1A, TUBA4A, the β-tubulin isoforms TUBB, TUBB4A, TUBB4B and all the γ-tubulin isoforms." (PMID 30126203, 2018). "Specifically, we found a low positive correlation between APLN and CYR61 (r = 0.16), a stronger correlation between APLNR and CYR61 (r = 0.68), a low correlation between APLNR and RIC8A (r = 0.20), and a moderate correlation between APLNR and TUBA1A (r = 0.58) in tumor patients." (PMID 39962271, 2025). "Furthermore, GSCA was used to examine the role of the TUBA family in tumour-related pathways to distinguish the functions of TUBA1C from those of other members of the TUBA family (TUBA1A and TUBA1B)." (PMID 36466547, 2022). "TUBA1A, DBI, and TUBB are up-regulated in tumor cells and down-regulated in periphery cells, and these are marker genes for the neoplastic cluster." (PMID 35327982, 2022). "Among them, ACAA1, GART, PDE9A, RPL3, TUBA1A, and TUBG1 gene products interact with several proteins known to be involved in the PRAD pathway and particularly important for apoptosis inhibition and tumor growth." (PMID 33712625, 2021). "Analyzing expression profile of BC tumors and tumor-adjacent normal breast tissues showed upregulation of TUBA1A, TUBA1C, TUBB and TUBB3 and downregulation of TUBB2A, TUBB2B, TUBB6, TUBB7P pseudogene, and TUBGCP2 in the tumor tissues compared to the normal breast tissues." (PMID 30126203, 2018).
cancer (10 papers, 2019 to 2025). A tumor composed of atypical neoplastic, often pleomorphic cells that invade other tissues. "The TUBA1A gene encodes α-tubulin, which forms a dimer with β-tubulin to generate tubulin α1c (TUBA1C), a protein known to upregulate in various cancers and strongly correlate with poor survival." (PMID 40974979, 2025). "CTNNBIP1 and TUBA1A were considered as proto-oncogenes in some of the cancers and the short transcript of two genes was related to the poor survival of the LUAD patients." (PMID 35954243, 2022). "The cancer pathway is also associated with two genes implicated in the cytoskeletal remodeling and network, ANXA2 and TUBA1A, linked to HCC and cell migration (i.e., metastasis development) thus predicting the fate of the NASH." (PMID 31717414, 2019). "High TUBA1A expression was correlated with mTOR and p38 MAPK pathways, which may control proliferation, growth, and survival of cancer cells; elevated TUBA1A expression was correlated with invasive subtypesand poor overall survival in GC patients." (PMID 36500393, 2022). "While ANKRD376 expression was significantly lower in cancer than in normal tissues, all other HRGs, except TUBA1A and ESRRP1, were significantly higher in cancer tissues." (PMID 36627705, 2023). "In addition, MTlo cancer cells expressed higher levels of SMTN1, TUBB, TUBA1A, and TUBA1B genes involved in microtubule turnover which contributes to cellular processes such as intracellular transport, cell division and migration, than MThi cancer cells did." (PMID 34483138, 2021).
neurodevelopmental disorder (5 papers, 2007 to 2024). A behavioral and cognitive disorder with onset during the developmental period that involves impaired or aberrant development of intellectual, motor, or social functions. "A recent article has identified high frequency of de novo mutations or variants (DNMs) in few genes which include PURA, SATB2, SCN1A, and TUBA1A and these are mostly found in cases of neurodevelopmental disorders (NDDs)." (PMID 39263390, 2024).
neurological diseases (4 papers, 2015 to 2024). "Together, the data support the TUBA1A mutation c.848A>G His283Arg as being causative of the neurological disorder and early death of the infant reported here." (PMID 39202391, 2024). "Recently, mutations in neuronal tubulin genes (e.g. TUBA1A, TUBB2B, TUBB3 and TUBA8) have been identified in patients suffering from nervous system disorders, underlining the importance of tubulin isotypes in MT dynamics during brain development and axon guidance." (PMID 26331477, 2015). "Missense variants in additional genes, random processes in cellular pathways, epigenetic factors, and chaperonin interactions could be possible modifiers and will require further research to completely understand the role of TUBA1A variation in neurological diseases." (PMID 35017693, 2022).
movement disorder (2 papers, 2020 to 2023). Neurological conditions resulting in abnormal voluntary or involuntary movement, which may impact the speed, fluency, quality and ease of movement. "Here, we show that significant reduction in developmental total α-tubulin resulting from a loss of function mutation in Tuba1a (Tuba1aND/+) causes an adult onset movement disorder." (PMID 32184299, 2020). "Here, we show that reduced function of TUBA1A, a tubulin isotype that has historically been characterized only in a developmental context, impacts the ability to maintain synapses over time and ultimately results in an adult-onset movement disorder." (PMID 32184299, 2020).